FN1 (fibronectin 1)
Diseases named in the same sentence as FN1 in open-access papers (continued):
Sharing a sentence is not in itself a finding about the gene and the disease.
tumor (continued). "At the molecular level, the epithelial biomarker CDH1 is downregulated, and the mesenchymal biomarkers N-cadherin (CDH2) and fibronectin (FN1) are upregulated in tumor buds, thus suggesting that tumor buds have mesenchymal characteristics." (PMID 28687755, 2017). "Slug and Snail, major EMT-related transcription factors, are known to induce fibronectin-1 and decrease E-cadherin expression during the progression of tumor metastasis." (PMID 27127545, 2016). "CAV1 and CAV2 were correlated with tumour growth and metastasis, and FN1 was a potential biomarker for some cancers, while ITGA1 and THBS1 were also associated with cancer risk." (PMID 27557147, 2016). "Taken together, we disclosed the role of chemotaxis and apoptosis in the fibrotic microenvironment-enhanced seeding of tumor cells and identified the fibroblast-derived FN1 and SPP1 as the central mediators in these processes." (PMID 27329720, 2016). "In this study, we used both cell and mouse models to demonstrate that fibrotic microenvironment enhanced the seeding and consequently the outgrowth of tumor cells in the lungs by activating the FN1/SPP1-ITGAV pathway." (PMID 27329720, 2016). "Second, both CM-FL and CM-FLF chemoattracted tumor cells and decreased the apoptosis of tumor cells, while silencing FN1 or SPP1 in fibroblasts attenuated the CM-FLF-promoted apoptosis resistance and chemotaxis of tumor cells." (PMID 27329720, 2016). "FBLN2, BIN1, FN1 and TNC examples suggest that the variants that are altered in the same direction in several cancer types have significant roles in tumor initiation and progression." (PMID 25908786, 2015). "The alterations of EMT-associated markers, such as: loss of epithelial genes CDH1, CDH3 and gain of mesenchymal genes CDH2 and FN1, as well as the adoption of a migratory mesenchymal phenotype were maintained in all the tumor-derived cell lines." (PMID 25361000, 2014). "We evaluated the attachment property of tumor cells to fibronectin (FN1) after sorting from GFP+E4-ECs." (PMID 25380486, 2014). "This investigation intended to evaluate the association between FN-1, ITGA-3, ITGB-5, MMP-2, and MMP-9 gene and protein expression levels in tumor tissue with clinical and histopathological neoplastic parameters of cancer dissemination." (PMID 24737953, 2014). "Spy1 also enhanced expression of the gene for fibronectin (FN1), which has been shown to mediate invasiveness and cell survival in other types of neural derived tumours." (PMID 25594028, 2014). "FN1 staining highlighted fibrous strands of the ECM between tumour cells and 96 cases (55.5%) resulted as FN1-low, whereas 77 cases (44.5%) as FN1-high." (PMID 24499539, 2013). "Several previous reports have suggested that a number of cellular genes such as human telomerase reverse transcriptase (hTERT) and Fibronectin 1 (FN1) were favored targets of HBV integration in HCC tumor tissue." (PMID 22962577, 2012). "One of these key regulators, FN1, was significantly upregulated in radioresistant tumor cells both at the mRNA and protein level." (PMID 23049743, 2012). "Fibronectin 1 is a glycoprotein involved in cell–matrix and cell–cell adhesion, cell migration and oncogene transformation, as well as in tumour invasion and metastasis." (PMID 20068563, 2010). "Relative mRNA expression levels were significantly higher in tumor than in healthy samples for FN1, MMP1, PLAU and SPARC (Wilcoxon test for paired data, p ≤ 0.002)." (PMID 19835631, 2009). "All except FN1 were found to be down-regulated in tumor samples with respect to their normal counterparts." (PMID 19116033, 2008). "Several upregulated genes (collagen type I, III, V, XI, fibronectin 1, versican) were related to tumor- ECM interactions and focal adhesion." (PMID 17389037, 2007). "Notably, the FN1 gene coding for the extracellular matrix glycoprotein fibronectin (FN) emerged as the EMT gene common to either tumor types." (PMID 41683575, 2026).
tumor (continued). "By comparing malignant and non‐malignant epithelial cells in PSC, malignant cells showed high expression of marker genes associated with epithelial–mesenchymal transition (EMT) and tumour metabolism regulation related genes, such as HMGA2, FN1, PDE10A, and PCAT1." (PMID 41469334, 2026). "Recent studies revealed that FN1 has been reported increased in a variety of tumours." (PMID 40638546, 2025). "Finally, FAP was associated with ECM and adhesion genes (FN1, COL5A1, SPOCK1, CDH13) and regulators of migration (NREP, SEMA5A), consolidating its central role in matrix deposition and tumor invasion, as previously shown." (PMID 41198614, 2025). "Additionally, FN1 is pivotal in the tumor microenvironment, mediating cell adhesion, migration, and signal transduction." (PMID 40772037, 2025). "Additionally, FN1 contributes to tumor microenvironment remodeling through interactions with other extracellular matrix proteins, further supporting tumor growth and dissemination." (PMID 40772037, 2025). "FN1 plays a crucial role in multiple tumors, nevertheless, tumor‐specific expression patterns for FN1 phosphorylation and glycosylation sites exist that may be one of the precise medicine targets." (PMID 39716938, 2025). "Additionally, platelets acquire PD-L1 from tumor cells through fibronectin 1, integrin α5β1, and GPIbα-dependent mechanisms, creating “tumor-educated” platelets with enhanced prothrombotic potential." (PMID 40725619, 2025). "BIRC5 showed affinity for anti-mitotic agents such as berberine, aligning with its function in cellular survival, whereas THY1 and FN1 were anticipated to engage with immune checkpoint inhibitors, reinforcing their promise in combinatorial therapy designed to augment anti-tumour immunity." (PMID 40475773, 2025). "Furthermore, FN1 signaling was significantly supporting cellular energy demands and maintaining immune suppression and homeostasis within the tumor microenvironment by regulating immune cell function." (PMID 40380260, 2025). "FN1 promotes the proliferation of tumor cells and tumor metastasis by regulating the EMT." (PMID 40223922, 2025). "Increasing studies have reported that FN1 plays vital roles in the metastasis of multiple tumours." (PMID 40638546, 2025). "Besides, TAMs deposit ECM proteins, like fibronectin 1, which promote tumor colonization and metastasis." (PMID 39940643, 2025). "Furthermore, we validated the expression and prognostic value of FN1 in GEO datasets and tumour samples." (PMID 40638546, 2025). "Another notable finding was gene FN1, which encodes yet another stromal CAF‐derived structural protein, and aside from being associated with invasiveness and tumor growth, some studies have shown that its expression positively correlates with immune infiltrates." (PMID 39245631, 2025). "Additionally, a risk score (RS) for predicting tumour relapse after NAC and cystectomy was calculated for each patient according to a mathematical algorithm containing FN1, VASP, and CEP63." (PMID 40149716, 2025). "FN1 knockdown inhibited tumor growth by reducing tumor cells aggregation, invasion, and migration." (PMID 40612060, 2025). "This also appeared to be consistent with the ccRCC patient tumor within the spatial transcriptomics dataset; however, there was a higher relative expression of FN1, which may reflect the diversity of cells within the tumor microenvironment." (PMID 40241258, 2025). "Moreover, tumor‐specific altered phosphosites and glycosites on FN1 are highlighted as potential therapeutic targets." (PMID 39716938, 2025). "Our study advances this by combining scRNA-seq, spatial transcriptomics, gene regulatory network analysis (pySCENIC), and intercellular communication analysis (CellChat) to elucidate a comprehensive tumor-immune interaction map, particularly around FN1+ tumor cells." (PMID 40612060, 2025).
tumor (continued). "As observed for the orthotopic model, the “boost” in CAF-dependent tumor initiation at a subcutaneous site could be prevented using CAFs with siRNA-mediated knockdown of FN1, whereas CAFs with ITGA5 knockdown produced tumors at 1 of 11 injection sites." (PMID 39785683, 2025). "Thus, our findings have uncovered the fibroblast–tumour cell crosstalk, mediated through the FN1/integrin/tyrosine kinase pathway." (PMID 41405822, 2025). "Compared to other tumor myeloid studies, we identified FN1 as a unique CSCC subcluster." (PMID 39354287, 2025). "In contrast, FN1 and L929 fibroblasts demonstrated minimal sensitivity, with reductions of only 0.2% ± 0.1% and 0.3% ± 0.2%, respectively, indicating preserved mitochondrial integrity in non-tumor cells." (PMID 41573726, 2025). "Meanwhile, FN1 secreted by CAFs enhances the expression of intercellular adhesion molecule 1, increases endothelial cell permeability, and facilitates the transendothelial migration of tumor cells, further promoting tumor cell extravasation." (PMID 40656546, 2025). "It was found that increased expression of FN1 mediated by NK cell receptor NKp46 could alter primary tumour architecture and result in the decreased metastases formation." (PMID 40638546, 2025). "Therefore, we used the tumor IMmune Estimation Resource (TIMER) Web Server to investigate FN1, CXCL8, IL1β, and ITIH4's function in the Comprehensive Analysis of tumor-infiltrating Immune Cells." (PMID 38637796, 2024). "The marked overexpression in cancer suggests that FN1 could be more easily detectable, which would facilitate its use in both diagnosis and early detection of tumor tissue." (PMID 39456895, 2024). "FN1 also plays a significant role in the tumor microenvironment." (PMID 38730286, 2024). "The metastatic intrahepatic tumor had higher FN1 expression." (PMID 39372792, 2024). "Furthermore, another study reported that high expression of FN1, observed in cancer cells, is a tumor suppressor gene." (PMID 38737262, 2024). "Meanwhile, another mono/macrophage cluster with heightened FN1 levels, which is associated with pro-angiogenic TAMs and necessary for cancer metastasis, was amplified in the tumor-bearing mice lacking Gpr84." (PMID 38349405, 2024). "By binding to cell receptors and forming fibronectin–fibronectin complexes, FN1 mediates communication between stromal and tumor cells, promoting angiogenesis, proliferation, and tumor metastasis, as well as interference with immune function and resistance to chemotherapy." (PMID 39456895, 2024). "Similarly, CTHRC1+GREM1+ myCAF communicated with SPP1+ macrophages and tumor cells through integrin signaling, where collagen/integrin pairs and FN1/integrin pairs were prevalent." (PMID 39075108, 2024). "Moreover, in GC, FN1 overexpression has been correlated with tumor aggressiveness and lymph node metastasis, suggesting its significance as a prognostic biomarker." (PMID 38913913, 2024). "FN1 secreted by TAMs is thought to facilitate tumour progression." (PMID 38903497, 2024). "For example, the elimination of Fn1 leads to inhibition of tumor angiogenesis." (PMID 38267885, 2024). "However, in the multivariate analyses, only fN1 or higher and R1 or more residual tumor were found as the significant predictors of poor prognosis." (PMID 38999874, 2024). "Interestingly, the extracellular matrix protein-encoding genes such as FN1, TIMP1, COL3A1, COL4A1, and COL2A1 were discovered in spatial cluster 8, regarded as tumor stroma tissues." (PMID 39257581, 2024). "Tumor cell migration can be inhibited by blocking the FN1 signaling pathway." (PMID 38737262, 2024). "Thus far, we have shown a correlation between profibrotic proteins in the primary CRC tumor and the expression of FN1 and SPP1 in the metastatic intrahepatic tumor." (PMID 39372792, 2024). "Similarly, in eCRSwNP, FN1 activated tissue-resident macrophages were observed to interact with basal EpCs via TREM2, which is a marker of tumor-associated macrophages." (PMID 38444858, 2024).
tumor (continued). "In contrast to FN1, downregulation of CNTN5 was shown to be associated with tumor metastasis." (PMID 39770638, 2024). "Genes such as MARCO, FN1, ACE, and CD163L1 are likely associated with the immunoregulatory functions of M2 macrophages, which typically promote tissue repair, anti-inflammatory responses, and support tumor growth." (PMID 39697346, 2024). "Furthermore, the expression of EMT genes and oncogenes, including Mmp3, Mmp7, Mmp8, Fn1, Vim, Foxc2, Ctnnb1, Lgr5, Axin2, cMyc, Ccnd1, and Yap1, was significantly high in the tumor of cohoused Nlrp12–/– compared with WT mice." (PMID 37581937, 2023). "Previous studies have shown that FN1 has both tumor-suppressive and -promoting characteristics." (PMID 37511126, 2023). "Additionally, FN1 inhibits tumour cell migration and promotes tumour metastasis by mediating intercellular and cell matrix adhesion." (PMID 37640804, 2023). "IHC results showed that FN1 protein was expressed in both tumor cells and stroma." (PMID 37026938, 2023). "FN1 protein expression was detected by IHC in 100 ESCC tumor specimens." (PMID 37026938, 2023). "However, the potential involvement of FN1 in modulating tumor immunity remains a relatively unexplored domain." (PMID 38239853, 2023). "Indeed, while LTBP1 was mainly expressed in tumor tissues, FN1 was highly expressed in fibroblasts of the stroma, suggesting a potential correlation between the overexpression of the two genes, which synergistically act to induce EMT." (PMID 37947594, 2023). "Furthermore, the resistance cannot be further inhibited with macrophages ablation, indicating a critical role of tumor cell–derived FN1 in driving resistance downstream of macrophages." (PMID 36749798, 2023). "In addition, FN1 expression was significantly higher in tumor cells compared with that in macrophages." (PMID 36749798, 2023). "The controversies in the literature may arise from the heterogeneous expression of FN1 within the tumor tissue, as we also demonstrated in this study." (PMID 37511126, 2023). "Furthermore, hsa_circ_0000285 and circ-CAMK2A enhance tumor growth and metastasis via upregulating FN1 expression through targeting specific adsorbed miRNAs in Gastric cancer and lung cancer respectively." (PMID 37819576, 2023). "In addition, these results demonstrate a trend towards decreased expression of Fibronectin 1, Myc, and Twist in the tumor-free and rTIMP2-treated wt mice." (PMID 38234759, 2023). "FN1 protein was highly expressed in 66 (66.0%) of the tumor tissues." (PMID 37026938, 2023). "In the present study, we found that FN1 protein was expressed in both tumor cells and stroma." (PMID 37026938, 2023). "FN1 interacts with MPO, which has controversial role in different diseases, and a type of its gene polymorphism leads to reduced anti-tumour activity that may play a role in development of CC." (PMID 36683048, 2023). "Firstly, we sought to determine the expression of the FN1 gene in patient-derived tumor specimens." (PMID 36922898, 2023). "Furthermore, IHC analysis of the tumour tissues demonstrated decreased levels of Ki67 and FN1 expression in the shFN1 group compared to the shCtrl group (p < .05)." (PMID 37784253, 2023). "Furthermore, SPP1-encoded proteins, including fibronectin 1 and osteopontin (OPN), are involved in processes such as wound healing and angiogenesis and they are closely associated with tumor prognosis." (PMID 37165402, 2023). "This study found that FN1 protein is expressed in tumor cells and stroma." (PMID 37026938, 2023). "Taken together, T/NK cells in PTC may form the immunosuppressive tumor microenvironment via FN1/ITGB1 interaction with other cells." (PMID 37733241, 2023). "High expression of FN1 protein in ESCC tumor tissue is an independent poor prognostic factor." (PMID 37026938, 2023). "Moreover, integrins have been reported in the literature as potential receptors for FN1, and upon this interaction, they have an important role in mediating tumor growth and metastasis." (PMID 37345058, 2023).
tumor (continued). "Further investigation of the regulatory mechanism may provide better insight into the precise roles of Hsp90ab1, MSN, CD44, and FN1 in the anti-tumor action of Lrp5 CM." (PMID 34976221, 2022). "The expression of FN1 in tumor invasion and migration is needed." (PMID 36081567, 2022). "Moreover, the expression of MMP2 and MMP9 was reversed when FN1 expression was knocked down in HOXD11-overexpressing cells, which suggested the indispensable role of FN1 in HOXD11-mediated tumor progression." (PMID 36151071, 2022). "One study demonstrated that silencing FN1 leads to increases in apoptosis-related proteins and reduced NF-kB, suggesting that FN1 overexpression in CA may aid tumour cells to evade apoptosis and to resist therapy by increasing NF-kB anti-apoptotic signalling." (PMID 35842572, 2022). "Silencing each of CD44 and FN1 reduced MSN's anti-tumor effect and their effects were additive." (PMID 34976221, 2022). "In OSCC, the ability of ZEB1-AS1 to bind miR-23a underlines its prooncogenic activity, with PSMA3-AS1 sequestering miR-136-5p, and thus promotes the upregulation of the downstream target gene FN1, with the lncRNA thus contributing to more invasive tumor cell growth through the miR-136-5p/FN1 axis." (PMID 36106022, 2022). "Similarly, analysis of macrophages from the 3 states revealed that there were distinct genes in the Tumor macrophages which includes genes like Cotl1, Tgfbi, Fos, and Fn1 along with complement activation genes C1qa, C1qb, and C1qc." (PMID 35851387, 2022). "We compared the tumor infiltration immune cells with different copy number variations including deep deletion, diploid/normal, arm-level deletion, arm-level gain, and high amplification for FN1 in STAD." (PMID 36081567, 2022). "Besides, FN1 is involved in NKp46 receptor-mediated interferon-γ production by natural killer cells, with respect to the control of tumor architecture and metastasis." (PMID 36035176, 2022). "For CHC patients, TERT and ALKBH5 are found to be integrated by HBV fragments in 4 tumors and 2 tumors respectively; interestingly, FN1 is also the only gene with HBV integration event occurred in more than 2 non-tumor samples, which is consistent with the results of ICC samples." (PMID 36123506, 2022). "Indeed, three of the four CAF index genes (TGFBI, TGFB2 and FN1) appear in the 938 DEG signature that separates C2 from C1 tumours." (PMID 36207323, 2022). "Additionally, immunofluorescence (IF) staining revealed high expression of fibronectin 1 (FN1) on the tumor spheroids cultured on polymer X." (PMID 36359204, 2022). "Moreover, FN1 was negatively related with tumor purity; thus, we finally identified it as a candidate gene, which strongly affects the tumor microenvironment and leads to tumor progression." (PMID 35893817, 2022). "A recent report showed that miR-1 demonstrates tumor suppressive activity in GBM by targeting FN1." (PMID 35954323, 2022). "The associations between the tumor purity and these 12 immune-survival-related genes were analyzed; the results revealed that four genes, i.e., FAM134B, ALDH3A2, SAV1, and RORC were positively related to tumor purity, and one gene (FN1) was negatively related to tumor purity." (PMID 35893817, 2022). "One IMT case with FN1 partner mutation had no response to crizotinib, but the tumor dramatically shrunk following lorlatinib neoadjuvant treatment followed by radical resection." (PMID 34722239, 2021). "Akt activation may be the downstream pathway of FN1 leading to tumor progression and poor prognosis in HNSCC." (PMID 34746236, 2021). "FN1 is an extracellular matrix glycoprotein involved in angiogenesis and tumor cell invasion." (PMID 34419060, 2021). "Besides, Fibronectin 1(FN1), predominantly overexpressed in many tumor tissues, was also involved in this pathway." (PMID 33892811, 2021).